MET (MET proto-oncogene, receptor tyrosine kinase)
Diseases named in the same sentence as MET in open-access papers (continued):
Sharing a sentence is not in itself a finding about the gene and the disease.
cancer (continued). "miR-96 is located at chromosome 7q32, a region containing several oncogenes including MET and BRAF and frequently amplified in cancers." (PMID 25333253, 2014). "HGF over-expression has also been demonstrated to be sufficient for neoplastic transformation in cells expressing normal levels of wild type MET, and HGF over-expression in transgenic mice drives the development of multiple cancers." (PMID 28548073, 2014). "Inhibition of MET using specific inhibitors is also known to adversely affect NSCLC cell viability and is the basis for several ongoing clinical trials aimed at testing the efficacy of MET inhibitors in NSCLC and other cancers." (PMID 24628993, 2014). "We have previously shown that luminal-type circulating tumor cells (CTCs) co-expressing the tyrosine-kinase MET and CD47, a ligand involved in cancer cell evasion from macrophage scavenging, are able to initiate metastasis in xenografts." (PMID 25230070, 2014). "MET belongs to the receptor tyrosine kinase (RTK) family and has been known to stimulate cancer cell growth." (PMID 25119929, 2014). "The second subgraph, which contains the largest number of component nodes, has its 95 nodes anchored to the known cancer proteins CTNNB1, APC, PTEN, TP63, MAPK4, MET, RAC1, and ROS1." (PMID 24516372, 2014). "PTPN12 has recently been shown to be downregulated in some cancers, leading to hyperactivity of RTKs (EGFR and MET) and hypersensitivity to TKIs that inhibit these kinases." (PMID 24189400, 2013). "A number of studies investigated the cross talk between MET and EGFR demonstrating its contribution to cancer growth, migration and invasion." (PMID 24167634, 2013). "A population of CTCs from patients with primary luminal cancer (expressing EPCAM, CD44, CD47 and MET) generated multi-site metastases when injected into mice." (PMID 24286369, 2013). "Due to its role in oncogenesis and cancer progression, c-MET is considered to be an important target in anticancer therapy, and some biological antagonists or monoclonal antibodies targeting c-MET have emerged which are known as c-MET TKI." (PMID 24205104, 2013). "Because genetic alterations in RTKs, such as FGFRs, EGFR, HER2, MET, ALK, and RET, drive human cancers, small-molecule inhibitors and human/humanized monoclonal antibodies targeted against RTKs have been developed as cancer therapeutics." (PMID 25364706, 2013). "The established role of c-MET and HGF/SF in the initiation and progression of a variety of human cancers has stimulated an extraordinary effort into the development of c-MET specific TKIs, with many of these currently under investigation in patients." (PMID 22511956, 2012). "Transcript levels of growth factors and their receptors, such as VEGFA, MET, ESR1, EGFR, and HER2 were relatively undetectable in CTCs compared to cancer cell lines." (PMID 22586443, 2012). "Among these cancer biomarker candidates, TFRC, MET and VEGFA are commonly amplified genes in tumors and their encoded proteins stained positive in more than 80% of malignancies from public databases." (PMID 22761861, 2012). "We expect that the two novel classes of anti-c-MET antibodies described here (LMH 80–82 and LMH 87–88) are potential therapeutic candidates for the treatment of human cancer." (PMID 22511956, 2012). "As it is the case with its better-known family member, MET, several lines of evidence suggest a role for RON in human cancer." (PMID 22613809, 2011). "We have generated assays to quantify the expression of c-MET, HGF, and HGF/c-MET ligand-receptor complexes in FFPE cell lines and human carcinomas and have cross-validated these measurements using independent biochemical methods." (PMID 21283737, 2011). "Various targeted inhibitory strategies are being undertaken in drug development to antagonise MET/HGF signalling in human cancers, including small-molecule kinase inhibitors, antibodies to the ligand HGF, and receptor MET itself." (PMID 19238632, 2008).
cancer (continued). "Biological effects of RON overexpression on cancer cells were investigated in vitro, and the prognostic significance of RON and/or c-met protein (MET) expression was analysed in a bladder cancer cohort (n=183)." (PMID 15870710, 2005). "In cancer tissue, upregulation of the HGF/MET signaling axis occurs mainly in a paracrine fashion." (PMID 40299447, 2025). "The constitutive and aberrant activation of c-MET mediated by NF-κB contribution provokes several downstream signaling pathways (MAPK, PI3K/AKT, STAT3) which subsequently promote cancer proliferation, survival, progression, angiogenesis, invasion and metastasis." (PMID 40022036, 2025). "This central role is largely attributed to aberrant c-MET/HGF signaling, which derives epithelial-to-mesenchymal transition, enhances cancer cell migration and invasion, stimulates angiogenesis through VEGF cross-talk, and contributes to chemoresistance, hallmarks frequently observed in TNBC." (PMID 41289612, 2025). "Since HGF and MET play important roles in cancer growth and metastasis, and STMN1S16 phosphorylation is regulated by HGF/MET signaling, the NMuMG and DU-145 cell lines were used to determine the impact of STMN1S16 phosphorylation on cell growth, migration, and invasion." (PMID 40723207, 2025). "Gene set enrichment analysis (GSEA) also revealed a significant downregulation of the hypoxia pathway and HIF-1α target genes upon ASH1L depletion, particularly those involved in cancer cell invasion (Snail, TGFB, and MET), extracellular matrix remodeling (MMPs and PLAU), and angiogenesis (VEGFs)." (PMID 40394007, 2025). "Intriguingly, the high-throughput anti-cancer compound screening assays demonstrated that TFF3 inhibition by AMPC synergized most effectively with compounds targeting four distinct RTKs, EGFR, VEGFR, c-KIT, and c-MET in MDA-MB-361 and BT474 cells." (PMID 39920140, 2025). "Consequently, there is a growing interest in formulating novel techniques that facilitate the concurrent use of MET and EGFR inhibitors, particularly in instances when MET serves as a targetable co-driver, such as in EGFR-mutant cancers." (PMID 40881676, 2025). "Genomic amplification of MET is frequently observed in human cancers, including non-small cell lung cancer (NSCLC), where it occurs in 25–75% of cases, depending on the study and criteria used to define overexpression." (PMID 40361420, 2025). "However, signal blockade by these HER2 and EGFR inhibitors induces compensatory responses in cancer cells, such as the overexpression and dimerization of other RTKs (e.g., HER3, MET), activating bypass pathways and ultimately leading to therapeutic resistance." (PMID 40872476, 2025). "Previous studies have highlighted the involvement of other RTKs in the response to EGFR inhibitors in cancer, including human epidermal growth factor receptor 2 (HER2), human epidermal growth factor receptor 3 (HER3), and MET (also known as hepatocyte growth factor receptor or HGFR)." (PMID 41514577, 2025). "Of 21 gene-cancer type pairs with significant interaction effects (FDR<0.05), 14 showed positive interaction effects with the largest effects found in FGFR3 in BLCA, CDK12 in STAD, and MET in LGG." (PMID 41415395, 2025). "Positive staining of MET and p-MET, which was defined as membranous staining with or without cytoplasmic staining, was observed in cancer cells." (PMID 40299443, 2025). "Furthermore, emerging evidence suggests a significant crosstalk between c-MET and TGF-β pathways contributing to immune evasion in cancer." (PMID 39664377, 2024). "Unlike chromosome 7 trisomy, MET gene amplification is specifically selected during cancer development and functions as a cancer driver." (PMID 38675409, 2024). "Combination of such two inhibitors has also been investigated in phase II clinical trial (NCT03392246) in EGFR mutant NSCLC cancer, and preliminary signal of activity were seen in phase I trial in a subgroup of patient, negative for MET expression." (PMID 38177190, 2024).
cancer (continued). "Additionally, the conditioned medium from c-MET-overexpressing cells significantly induced neutrophils to secrete lipocalin 2 (LCN2), which in turn promoted the self-renewal of cancer stem cells, a process reported to induce immunosuppression." (PMID 39201787, 2024). "Additionally, most of the research presented in this review is based on in vitro experiments and more research needs to be carried out to discern the viability of targeting metabolic pathways downstream of MET and RON signaling in cancer in vivo." (PMID 39062731, 2024). "Moreover, numerous oncogenic drivers (ALK, BRAF, EGFR, MET, NRG1, NTRK1/2/3, RET, and ROS1) involved in sole reciprocal fusions were found in those cancers." (PMID 39254060, 2024). "These insights required the generation of high-quality quantitative data on the dynamics of HGF signal transduction and thus shed new light on the complex regulation of MET in MASLD, while MET was so far primarily studied in the context of liver regeneration or cancer." (PMID 38216754, 2024). "Increased MET and HGF levels have been reported in various human cancers." (PMID 39519229, 2024). "A β-adrenoceptor-mediated induction of MET was previously reported in other non-tumorigenic cells (bronchial epithelial cells) and in cancer cell models, namely in oral squamous cancer cells." (PMID 38334654, 2024). "This indicates that MET’s role in resistance might extend beyond individual receptors, potentially affecting a range of ERBB-driven cancers, and this highlights the need for targeting this pathway in combinational treatment strategies." (PMID 38675409, 2024). "Moreover, the interactions between ADAM10 and MET could influence how these proteins are sorted into EVs, thereby impacting intercellular communication and the spread of signaling molecules in physiological and pathological processes, including cancer metastasis." (PMID 39769452, 2024). "c-MET and SPON2, as transcriptional targets of MACC1, induced metastasis in xenograft and genetically modified mouse models, and is closely related to the metastasis of cancer patients." (PMID 39695175, 2024). "Asian patients (China Pan-Cancer, OrigiMed, Nature 2022) had the highest incidence of MET fusions, at approximately 1.05%, which was much higher than the second highest incidence (MSK MetTropism, MSK, Cell 2021, incidence of MET fusions: 0.22%)." (PMID 38195556, 2024). "Furthermore, c-MET catalyzes the activation of mitogen-activated protein kinase (MAPK) and PI3K/Akt pathways, culminating in processes critical to cancer progression, such as cell proliferation, angiogenesis, and invasion." (PMID 39664377, 2024). "Several studies have reported that c-MET expression in CTCs or c-MET+ CTCs can be detected in patients with cancer; however, survival analysis has not been conducted." (PMID 38238761, 2024). "For instance, MET fusions in lung cancer commonly undergo MET 14 skipping due to RNA alternative splicing, a phenomenon not observed in other cancer types like glioma and colorectal cancer." (PMID 39254060, 2024). "Based on the correlation of HAI-1 with CRC prognosis and cetuximab response in cancer databases and cell lines, we hypothesized that HAI-1 addition or overexpression would induce cetuximab sensitivity in HGF/MET-dependent cetuximab-resistant lines." (PMID 38212428, 2024). "MET and its ligand, HGF, participate in signaling pathways involved in oncogenic processes, including cell proliferation regulation, invasion, angiogenesis, and cancer stem cell regulation." (PMID 39519229, 2024).
cancer (continued). "The expression of PD-L1 on cancer cells can be directly upregulated by MACC1 itself, or through secondary factors such as HGF/c-MET, via activated STAT1/3, PI3K/Akt, or Wnt/β-catenin signaling, from metabolic alterations or by promoting cellular stemness via Oct4/NANOG/LGR5." (PMID 39580452, 2024). "Consequently, c-MET and HGF have emerged as prominent targets for molecularly targeted cancer therapies." (PMID 39335535, 2024). "Although targeting HGF/c-MET has improved clinical outcomes in some cancers, monotherapy targeting HGF/c-MET has been unsuccessful in proving considerable clinical efficacy in several cancers." (PMID 39355533, 2024). "By downregulating the combined molecular targets, such as c-MET, STAT3, and AKT and their phosphorylated forms, the activation and overexpression of cancer stem cell-like cells is suppressed along with drug resistance signaling, hence improving the overall survival of the patients." (PMID 37373393, 2023). "Interestingly, HER3 has been shown to be able to interact with MET, IGF-1R, or FGFR3 in various human cancers." (PMID 37716943, 2023). "Regarding the effects of HER3 and MET on cancer cell proliferation, the combined stimulation of both ligands enhanced cell proliferation more than either ligand alone, suggesting that HER3 and MET contribute to cell proliferation in a concerted manner." (PMID 36751113, 2023). "Co-expressed genes (PXN, ITGA3, TES, and MET) were identified and analyzed by FunRich with CAV1 and CAV2, revealing a significant correlation with focal adhesion (p < 0.001), which has a vital influence on cancer progression." (PMID 36830672, 2023). "To define the role of the HGF/MET axis in this complex process, we genetically knocked out the MET gene in cancer cells that were not dependent on MET signaling for their growth." (PMID 37345079, 2023). "Anecdotal evidence that patients with cancers with MET fusions may benefit from MET inhibitors comes from a case report of a woman with NSCLC and brain metastases harboring an HLA–DRB1–MET fusion." (PMID 36999986, 2023). "Moreover, FYN is involved in the regulation of multiple cancer-related signaling pathways, including interactions with ERK, COX-2, STAT5, MET and AKT." (PMID 36740671, 2023). "Additionally, due to the activation of receptor tyrosine kinase (c-MET), the infiltration of neutrophils by S100A4 and increased expression of invasion-promoting integrin β1 in cancer cells is observed." (PMID 37569531, 2023). "However, miR-410 effectively targets c-MET and Angiotensin II Type 1 receptor (AGTR1) to suppress cancer." (PMID 38201476, 2023). "In recent years, the large, growing number of detected MET alterations in NSCLC and other carcinomas as well as the better understanding of the diverse biology driving MET dysregulation in cancer has shown the important role of this kinase for targeted therapy approaches." (PMID 37296895, 2023). "Sentani and colleagues reported that mixed type GC showed a characteristically expression of cancer stem cell-related molecules (CD44, CD133, and ALDH1), receptor tyrosine kinase molecules (EGFR, c-MET, and HER2), and chromosomal instability compared to pure type GC." (PMID 37950183, 2023). "Tivantinib inhibited cell viability with similar potency in both c-MET-addicted and nonaddicted adult carcinoma cells, pointing to alternative mechanisms of action." (PMID 36839989, 2023). "Hepatocyte growth factor (HGF) is mainly secreted by CAFs and binds to the receptor, MET, on cancer cells, which activates the downstream signaling involving AKT, ERK/MAPK, and STAT3, and then enhances cancer cell survival, EMT, migration, invasion, proliferation, and chemotherapy resistance." (PMID 35327514, 2022). "In addition, according to the results from our 24 pairs of cancer and adjacent-tissue samples, the expression levels of TSC1, MET, and ITGA6 in cancer were significantly higher than those in adjacent normal tissues." (PMID 36261830, 2022).
cancer (continued). "In addition, USP22, EGFR, MET and MAPK were reported to act as targets of miR-30e-5p in human cancers." (PMID 34998399, 2022). "In present study, we reported that IFITM3 served as a novel modulator of HGF/MET-mediated AKT signaling that suppressed FOXO3 (Forkhead Box O3), consequently leading to c-MYC (MYC proto-oncogene) mediated cancer proliferation, migration, stemness and drug resistance." (PMID 35941699, 2022). "In particular, c-MET and NTRK1 were identified as regulators of matrix alignment and may serve as novel targets within the cancer stroma." (PMID 36530465, 2022). "The HGF/c-MET axis is activated in cells with increased HGF and c-MET expression, promoting cell proliferation, motility, angiogenesis, and epithelial-to-mesenchymal transition (EMT), ultimately leading to cancer cell growth and metastasis." (PMID 35630066, 2022). "One of the key hurdles in cancer therapy is overcoming drug resistance developed within heavily pre-treated refractory tumors and targeting the HGF/c-MET pathway could be a promising tool for addressing this." (PMID 36034555, 2022). "A pan-cancer analysis then confirmed that CDK6 and MET are potential targets upon which T. hemsleyanum may exert antitumor action, especially in ACC, CESC, LGG, and PAAD." (PMID 35480115, 2022). "In addition, activation of MET regulates E-cadherin and vimentin to induce EMT and promotes cancer cell proliferation through activating downstream targets such as c-Myc." (PMID 35301291, 2022). "The role of MET in EGFR exon 20 insertion mutant driven cancers has not been investigated and only one patient enrolled in the CHRYSALIS trial was identified to have baseline MET amplification." (PMID 34913823, 2022). "All of this was the initial knowledge about MET in cancer; nevertheless, the development of target therapies against MET was not initiated until the discovery of METex14, which is by far the most common MET mutation." (PMID 36430388, 2022). "In contrast, MET germline mutations have been implicated in many cancers, including KRIP, and it was not surprising that we also found MET germline mutations in this study." (PMID 36451132, 2022). "Indeed, our results revealed that combined anti-PD-1/-MET antagonism resulted in high levels of PDAC cytotoxicity in both in vitro and in vivo cancer models." (PMID 35804822, 2022). "We found that cancer cell lines overexpressing the MET oncogene were less sensitive to olaparib than cell lines not expressing or showing lower levels of MET expression." (PMID 35628590, 2022). "EGFR, KIT, MET, PPARG, and STAT5A were enriched in the Pathways in cancer, CAV1, EGFR, and MET were enriched in the Proteoglycans in cancer, and MET and PPARG were enriched in the Transcriptional misregulation in cancer." (PMID 35063044, 2022). "Second, as ICAM-1 acted as an adapter protein to regulate the c-MET-SRC axis in CRC, further research is required to determine whether it acts as an adapter protein in other types of cancer." (PMID 35487888, 2022). "Multiple pre-clinical studies reviewed above suggest that the HGF/c-MET pathway is important for protecting cancer cells from insult, and so it follows that anti-HGF/c-MET therapy could be effective as an adjuvant to other cytotoxic therapies." (PMID 36034555, 2022). "For the first time, we demonstrated that THEMIS2 specifically enhanced MET activating phosphorylation by suppressing the association of protein-tyrosine phosphatases 1B (PTP1B) with p-MET and MET, which accounted mainly for THEMIS2-mediated effect on cancer stemness and chemoresistance." (PMID 34974522, 2022). "One of the key pathways that may mediate cancer-stromal interactions is the hepatocyte growth factor (HGF) and its receptor c-MET pathway." (PMID 36591282, 2022). "c-MET and RON have both essential functional roles in embryonic development and organogenesis and are overexpressed and/or aberrantly activated in various cancer types suggesting their potential importance as therapeutic targets." (PMID 35069735, 2022).